ALK (ALK receptor tyrosine kinase)
Diseases named in the same sentence as ALK in open-access papers (continued):
Sharing a sentence is not in itself a finding about the gene and the disease.
lung cancer (continued). "We showed a significant prevalence in ALK IHC positive NSCLC in HR+ NSCLC compared to HR- NSCLC; this combination has not been studied much in lung cancer and may be worth further investigation first by evaluating HR+ in ALK fusion NSCLC." (PMID 37700839, 2023). "However, unlike EGFR or ALK, BRAF has relatively low prevalence in lung cancer, and this study was conducted with untreated patients." (PMID 36076922, 2022). "Despite ALK-positive patients accounting for a small proportion of NSCLC, the absolute number of patients with ALK-positive NSCLC is not small due to the greater worldwide incidence of lung cancer." (PMID 34530849, 2021). "There may be two speculations for that result: one is that the phenomenon could be specific for ALK-positive lung cancer, and the other is that cases with FISH-positive in tissue and ALK-negative in platelets were false positives of tissue FISH assay." (PMID 31154543, 2019). "In conclusion, our results corroborate the hypothesis that combination ALK and IGF-1R inhibition overcomes primary crizotinib resistance in ALK+ lung cancer cells, but does not necessarily overcome acquired crizotinib resistance." (PMID 29066738, 2017). "Similarly, crizotinib showed stronger inhibition of lung cancer cell lines with a recurrent gene fusion between EML4 and ALK than it did in those without the fusion gene." (PMID 27070423, 2016). "However, other factors (mainly related to driver gene alterations in lung cancer, such as EGFR and ALK) were not reported, as well as the information about treatment with targeted therapy for oncogene-addicted tumours (which may confound the results in the adenocarcinoma subset)." (PMID 28846697, 2017).
non-small cell lung carcinoma (1,287 papers, 2008 to 2026). A group of at least three distinct histological types of lung cancer, including non-small cell squamous cell carcinoma, adenocarcinoma, and large cell carcinoma. "This case expands the spectrum of ALK rearrangements and highlights the critical role of molecular profiling in guiding adjuvant treatment decisions for early-stage, high-risk non-small cell lung cancer (NSCLC)." (PMID 42137140, 2026). "Lorlatinib, a third-generation ALK tyrosine kinase inhibitor (TKI), effectively targets most single ALK mutations in ALK-positive non-small cell lung cancer (NSCLC), while acquired resistance remains a major clinical challenge." (PMID 42129432, 2026). "ALK fusion is a key driver mutation in non-small cell lung cancer, typically present as a primary genetic alteration." (PMID 41737422, 2026). "Anaplastic lymphoma kinase (ALK) has been implicated as a key driver in several malignancies, including non-small cell lung cancer and anaplastic large cell lymphoma, through various activating mutations, fusions, and amplifications." (PMID 40872569, 2025). "Aberrant ALK signaling is implicated in the pathogenesis of multiple cancers, including non-small cell lung cancer, making it a well-established target for therapeutic intervention." (PMID 40872569, 2025). "In a previous matched tissue-blood analysis, 21% of ALK-positive non-small cell lung cancer patients showed multiple tumor-specific EML4::ALK variants, indicating the existence of fusion-defined tumor heterogeneity evident at the genomic level." (PMID 40041857, 2025). "For example, the EML4 (echinoderm microtubule-associated protein-like 4)-ALK (anaplastic lymphoma kinase) fusion gene has been linked to non-small cell lung cancer, while BCR-ABL has been associated with chronic myeloid leukemia." (PMID 40584293, 2025). "Anaplastic lymphoma kinase (ALK) gene fusions represent one of the most common driver mutations in non-small cell lung cancer (NSCLC)." (PMID 41458607, 2025). "Among the ALK-targeted tyrosine kinase inhibitors (TKIs), Enshatinib is approved as monotherapy for patients with locally advanced or metastatic non-small cell lung cancer (NSCLC) harboring ALK-positive mutations." (PMID 41282618, 2025). "A subsequent value of implementation analysis quantified how limited testing capacity for ALK mutations reduced the incremental net benefit of crizotinib for people with EGFR-negative non-small cell lung cancer." (PMID 40726112, 2025). "Value of serum tumor markers for predicting EGFR mutations and positive ALK expression in 1089 Chinese non-small-cell lung cancer patients: A retrospective analysis." (PMID 40977824, 2025). "The therapeutic landscape for brain metastases in EGFR and ALK-mutated non-small cell lung cancer has been fundamentally transformed by the advent and evolution of tyrosine kinase inhibitors." (PMID 40981198, 2025). "Anaplastic lymphoma kinase (ALK) rearrangements are driver mutations that occur in approximately 3%–7% of non-small cell lung cancer (NSCLC) cases, primarily in the lung adenocarcinoma subtype." (PMID 40376302, 2025). "The discovery of anaplastic lymphoma kinase (ALK) tyrosine kinase gene rearrangement mutations in non-small cell lung cancer (NSCLC) has driven continuous advancements in ALK-targeted therapies." (PMID 40640095, 2025). "Lorlatinib, a tyrosine kinase inhibitor used in anaplastic lymphoma kinase (ALK)-positive non-small cell lung cancer (NSCLC), is associated with adverse events, including hyperglycemia." (PMID 41322009, 2025). "In non-small cell lung cancer, mutations of the anaplastic lymphoma kinase (ALK) gene are predictive biomarkers for response to ALK inhibitors like brigatinib." (PMID 40261443, 2025).
non-small cell lung carcinoma (continued). "Genetic characterization of oncogenic driver mutations (EGFR, KRAS, ALK, ROS) has transformed the management of non-small cell lung cancer (NSCLC) therapy with the introduction of molecularly targeted therapies, allowing an individualized treatment approach." (PMID 38643157, 2024). "Clinical studies in non-small cell lung cancer have shown alectinib (an inhibitor of ALK and ALK-variant proteins resulting from rearrangement of the ALK locus) to be an effective therapy in tumors with ALK rearrangements." (PMID 39205743, 2024). "Studies have shown that crizotinib prolongs the survival of patients with ALK mutation-positive non-small cell lung cancer." (PMID 38558328, 2024). "ALK gene fusion is a well-known driver mutation present in 3–7% of cases diagnosed with non-small cell lung cancer (NSCLC)." (PMID 38379102, 2024). "ATLANTIC is a phase 2, open-label, single-arm trial that assessed the effect of durvalumab as a third-line or later treatment for advanced non-small cell lung cancer in patients with EGFR mutations or ALK rearrangements." (PMID 38758372, 2024). "Anaplastic lymphoma kinase (ALK) gene fusion is a classic driver mutation in non-small cell lung cancer (NSCLC); however, ALK double-fusion variants in NSCLC have rarely been reported." (PMID 38379102, 2024). "Chromosomal rearrangements encoding the anaplastic lymphoma kinase (ALK) gene in non-small cell lung cancer (NSCLC) can be detected in 3-8% of cases." (PMID 38789868, 2024). "The 11 currently reportable or actionable variants for non-small cell lung cancer (NSCLC) were extensively verified (n=126) (ALK, EGFR, BRAF, KRAS, NTRK 1/2/3, ROS, RET, MET, ERBB2)." (PMID 36522176, 2024). "ALK mutations are more common (~ 2.8%), but most cancers with this mutation are non-small cell lung cancer, melanoma, and colorectal, which are more common tumor types." (PMID 36639625, 2023). "Acquired anaplastic lymphoma kinase (ALK) mutation is the major resistant mechanism to ALK tyrosine kinase inhibitors (TKIs) in non-small cell lung cancer (NSCLC) patients." (PMID 38149055, 2023). "ALK gene fusions are observed in a subset of non-small cell lung cancers and are associated with a heightened response to ALK inhibitors such as crizotinib, ceritinib, and alectinib." (PMID 37444584, 2023). "The development of therapeutic agents targeting products of epidermal growth factor receptor (EGFR) gene mutation and anaplastic lymphoma kinase (ALK) rearrangements has improved survival in patients with non-small-cell lung cancer." (PMID 37835855, 2023). "Similar to the discovery of NPM1-ALK in ALCL, the echinoderm microtubule-associated protein-like 4 (EML4)-ALK fusion gene was discovered as a cancer driver gene, which is detected in ~7% of patients with non-small cell lung carcinoma (NSCLC)." (PMID 37894456, 2023). "Alectinib, a second-generation tyrosine kinase inhibitor, is a targeted therapy used in patients with non-small cell lung cancer found to have anaplastic lymphoma kinase (ALK) mutations." (PMID 37454087, 2023). "The EML4 (echinoderm microtubule-associated protein-like 4)-ALK (anaplastic lymphoma kinase) fusion gene in non-small-cell lung cancer (NSCLC) was first identified in 2007." (PMID 36982897, 2023). "The first description of echinoderm microtubule-associated protein-like 4 (EML-4)-ALK rearrangement in non-small-cell lung cancer (NSCLC) was reported in a Japanese male former smoker in 2007." (PMID 37232842, 2023). "A mutation in anaplastic lymphoma kinase (ALK) was reported to drive tumor formation in 5% of the non-small-cell lung cancer population and led to the discovery of ALK blockers such as crizotinib and ceritinib." (PMID 37397557, 2023). "CER has been approved for the treatment of patients with non-small-cell lung cancer (NSCLC) harboring the anaplastic lymphoma kinase (ALK) mutation gene." (PMID 37893531, 2023).
non-small cell lung carcinoma (continued). "Some of these fusions or mutations showed, to some degree, clinical significance, for instance, like ALK positive non-small cell lung cancer (NSCLC), ROS1 positive NSCLC has more high risk of central nervous system metastasis." (PMID 36998041, 2023). "Studies have reported that concurrent EGFR/ALK co-mutation in non-small cell lung cancer patients is rare, with a prevalence ranging from 0.1% to 1.6%." (PMID 37705536, 2023). "Crizotinib, the first clinically approved drug to target ALK, is a tyrosine kinase inhibitor that was approved for use in echinoderm microtubule-associated protein-like 4 EML4-ALK-positive non-small-cell lung cancer (NSCLC)." (PMID 35508387, 2022). "Anaplastic lymphoma kinase (ALK)–tyrosine kinase inhibitors (TKIs) have been approved for the therapy of locally advanced non-small cell lung cancer (NSCLC) caused by ALK rearrangement." (PMID 35366157, 2022). "Generalizing clinical studies of single immune checkpoint inhibitors in patients with ALK mutated advanced non-small cell lung cancer." (PMID 36591504, 2022). "Anaplastic lymphoma kinase (ALK) mutation plays an important role in the occurrence and development of non-small cell lung cancer." (PMID 36290895, 2022). "Anaplastic lymphoma kinase (ALK) isa kinase whose dysregulation in humans is associated to numerous oncologicaldiseases including non-small cell lung cancer and anaplastic largecell lymphoma." (PMID 35303411, 2022). "Anaplastic lymphoma kinase (ALK) fusions represent the second most common oncogenic driver mutation in non-small cell lung cancer (NSCLC)." (PMID 36002192, 2022). "Concluding remarks clinical studies in ALK mutated advanced non-small cell lung cancer receiving immunotherapy combined with chemotherapy." (PMID 36591504, 2022). "Concluding remarks clinical studies in ALK mutated advanced non-small cell lung cancer receiving immunotherapy combined with targeted therapy." (PMID 36591504, 2022). "Anaplastic lymphoma kinase (ALK) gene rearrangement is one of the driver mutation genes that induce non-small-cell lung cancers (NSCLCs)." (PMID 36612200, 2022). "For example, the appreciation that mutations in the anaplastic lymphoma kinase (ALK) gene are associated with non-small-cell lung cancer led to the emergence of ALK1 inhibitors as an outstanding treatment strategy." (PMID 35740736, 2022). "Rearrangements of the anaplastic lymphoma kinase (ALK) gene are well-established risk factors for non-small cell lung cancer (NSCLC)." (PMID 35454856, 2022). "Concluding remarks clinical studies in ALK mutated advanced non-small cell lung cancer receiving immune checkpoint inhibitors in combination with anti angiogenic inhibitors." (PMID 36591504, 2022). "Rearrangements of the anaplastic lymphoma kinase (ALK) gene have been identified in approximately 3–7% of non-small cell lung cancer (NSCLC) patients, with echinoderm microtubule-associated protein like-4 (EML4) representing the most common fusion partner." (PMID 34271921, 2021). "MYC was previously implicated in different ALK dependent malignancies including non-small cell lung cancer neuroblastoma and ALK+ ALCL." (PMID 33310759, 2021). "Several studies have demonstrated the suitability of serial ALK variants assessment for disease monitoring of ALK-positive non-small-cells lung cancer (NSCLC)." (PMID 34282791, 2021). "A well-known PTK associated with EGFR is Anaplastic lymphoma kinase (ALK) was identified in lymphoma, non-small cell lung cancer is the most common ALK-positive disease." (PMID 35356629, 2021). "For example, crizotinib, a selective c-MET inhibitor, was approved for marketing by the US FDA for patients with ALK mutation-positive non-small-cell lung cancer (NSCLC)." (PMID 34804015, 2021). "ALK inhibitors, such as Crizotinib and Ceritinib, have been widely used to treat cancers with mutations of ALK, especially for non-small cell lung cancers." (PMID 33738250, 2021).
non-small cell lung carcinoma (continued). "Rearrangements in the Anaplastic Lymphoma Kinase (ALK) gene have been implicated in 5–6% of all non-small cell lung cancers." (PMID 33806977, 2021). "ALK mutations are common in many adult cancers and are the most prevalent in non-small-cell lung cancer (NSCLC) and anaplastic large cell lymphoma (ALCL)." (PMID 34575503, 2021). "The use of lorlatinib, an anaplastic lymphoma kinase (ALK) inhibitor for the treatment of ALK-positive metastatic non-small cell lung cancer, is associated with dyslipidemia in over 80% of patients." (PMID 36645013, 2021). "The most promising responses were seen in HER2-positive breast cancer and in non-small cell lung cancer (NSCLC) patients with ALK translocations or EGFR mutations." (PMID 34077750, 2021). "One of the three mqTrans biomarker genes encodes a ligand for human kinase ALK, which is involved in the non-small cell lung cancers." (PMID 32656193, 2020). "Of enormous scientific interest has been the discovery of somatic driver mutations in this malignancy, with up to 10 and 4% of non-small cell lung cancers carrying epidermal growth factor receptor mutations and ALK translocations, respectively." (PMID 33272232, 2020). "The ALK protein cargo in EVs following irradiation was also implicated in driving tumour growth and compromising therapeutic efficacy of ALK inhibitors in non-small-cell lung carcinoma (NSCLC)." (PMID 30682793, 2019). "7-epi-clusianone has the ability to induce cell death in non-small cell lung cancer cell lines and inhibit an ALK tyrosine kinase mutation responsible for acquired resistance to treatment." (PMID 31816878, 2019). "Only one alteration in the anaplastic lymphoma kinase (ALK) locus was found in hiPSCs generated with mRNA that was shown to predispose to neuroblastoma colorectal adenocarcinoma and non-small-cell lung carcinoma." (PMID 31105870, 2019). "In 2007, the echinoderm microtubule-associated protein-like 4 (EML4)–anaplastic lymphoma kinase (ALK) gene rearrangement was first discovered as a driver oncogene for non-small cell lung cancer (NSCLC)." (PMID 31608224, 2019). "Neuromedin U (NMU) is implicated in the development of ALK inhibitor resistance in non-small cell lung cancer." (PMID 31681584, 2019). "We also found novel somatic mutations in another receptor kinase gene such as ALK, which is known to be mutated or amplified in various other cancers such as lymphomas and non-small cell lung cancers." (PMID 31480474, 2019). "These molecular subtypes of EGFR-mutated or ALK+ non-small cell lung cancer (NSCLC) serve as a perfect clinically validated example of “clean tumors” as these tumors usually do not have high mutational burden, occur in younger patients, and in non-smokers." (PMID 29871670, 2018). "A small number of small molecule tyrosine kinase inhibitors have recently received FDA approval for treatment of non-small cell lung cancer (NSCLC) with EGFR mutations or ALK translocations." (PMID 29455673, 2018). "In differentiated tissues, ALK can be activated by translocations or mutations making it an oncogene in a variety of malignancies, such as non-small cell lung cancer, anaplastic large cell lymphoma, neuroblastoma and many more." (PMID 30290811, 2018). "The exact action of this ALK mutation on oncogenesis is still unclear, however it has been implicated in numerous malignancies including non-small cell lung cancer." (PMID 29541442, 2018). "On-target resistance mechanisms found in one-third of patients receiving anaplastic lymphoma kinase (ALK) tyrosine kinase inhibitors (TKIs) are secondary ALK mutations in ALK-rearranged non-small cell lung cancer (NSCLC)." (PMID 30453899, 2018). "Epidermal growth factor receptor (EGFR) mutations and the anaplastic lymphoma kinase (ALK) rearrangement are the two most common druggable targets in non-small cell lung cancer (NSCLC)." (PMID 29164298, 2018).